CTLA4 (cytotoxic T-lymphocyte associated protein 4)
Diseases named in the same sentence as CTLA4 in open-access papers (continued):
Sharing a sentence is not in itself a finding about the gene and the disease.
breast carcinoma (continued). "Elevated CTLA-4 expression on breast cancer cells locally correlates with increased TILs and, counterintuitively, with improved clinical outcomes in multiple cohorts, particularly in HER2+ and basal-like subtypes." (PMID 41550427, 2025). "Multiple immunotherapies, such as CTLA-4-, PD-1-, and PD-L1-specific immune checkpoint antagonists, have been developed in breast cancer to effectively enhance patient survival." (PMID 39483334, 2024). "Triple therapy, involving radiotherapy alongside anti-CTLA-4 and anti-PD-L1 antibodies, has exhibited notable effectiveness in breast cancer treatment, in which radiotherapy enhances the impact of immune checkpoint inhibitors." (PMID 39188717, 2024). "Follow-up studies further demonstrated that fractionated radiotherapy in combination with anti-CTLA-4 treatment induced a more significant systemic antitumor effect in a mouse breast cancer model compared with single-dose radiotherapy." (PMID 39403601, 2024). "In inflamed cancer types including breast cancer, NcDase expression correlated strongly with the expression of the markers of immune regulation (CTLA4, LAG3, PDCD1, SIGLEC15)." (PMID 38302493, 2024). "A clinical trial is currently underway to examine the impact of combining anti-CTLA-4 mAB with paclitaxel and gedatolisib on both antitumor efficacy and tolerance in breast cancer patients." (PMID 38956700, 2024). "These preclinical observations provide evidence for the rationale of combining epigenetic modulators with anti-CTLA-4 therapy in breast cancer." (PMID 38956700, 2024). "Further, peripheral blood mononuclear cells (PBMCs) of breast cancer patients express the HVEM gene in similar levels to the approved target immunotherapy CTLA-4." (PMID 38785930, 2024). "This indicates that combination therapy with carbon ion irradiation and CTLA4 blockade established a memory response against breast cancer." (PMID 38474078, 2024). "These preliminary results indicate that gut microbial bacteria influence anti-CTLA-4 efficacy and antitumor response in breast cancer, making the gut microbiome therapeutically relevant for immunotherapy." (PMID 38956700, 2024). "The combination of anti-CTLA-4 therapy with cancer vaccines presents therapeutic promise, particularly for breast cancer patients with poor immunogenicity." (PMID 38956700, 2024). "CTLA4-based immune checkpoint inhibitors have significantly changed the landscape of breast cancer therapy." (PMID 38891044, 2024). "However, for late-stage breast cancer patients, the efficacy of current treatments is limited; these treatments include cancer immunotherapy, such as immune checkpoint inhibitors targeting programmed cell death protein (PD-1) and cytotoxic T-lymphocyte-associated antigen 4 (CTLA-4)." (PMID 38903515, 2024). "TLR agonists are being evaluated in combination with immune checkpoint inhibitors (e.g., anti-PD-1, anti-PD-L1, anti-CTLA-4) for breast cancer treatment." (PMID 38903515, 2024). "Targeting CTLA-4 with inhibitors such as ipilimumab has garnered attention as a therapeutic strategy in breast cancer." (PMID 39493764, 2024). "In a trial with 17 women who had metaplastic breast cancer and had already tried several treatments, the combination therapy with nivolumab (a PD-1 inhibitor) and ipilimumab (a CTLA-4 inhibitor) resulted in an overall response rate of 18%." (PMID 39539894, 2024). "In our research, we employed common inbred BALB/c mice, used the mouse breast cancer (4T1) model, and administered a combination of PD‐1 and CTLA‐4 inhibitors over multiple sessions." (PMID 39001676, 2024). "They found anti-cancer effects of γ-irradiation in combination with anti-CTLA4 mAb on breast cancer, with protection against metastases." (PMID 38474078, 2024).
breast carcinoma (continued). "Inhibition of CXCR4-CXCL12 mobilizes CD8+ T cells in the tumor and synergizes with anti-PD-L1 immunotherapy; CXCR4 antagonist AMD3100 is used to improve efficacy of bortezomib treatment and anti-PD-1 and anti-CTLA-4 therapy in breast cancer mouse models." (PMID 39596815, 2024). "The efficacy of anti-CTLA-4 therapy also depends on commensal bacteria composition as studies have shown the gut microbiome is involved in breast cancer development and response to therapy." (PMID 38956700, 2024). "Combination of anti-PD1 and anti-CTLA4 therapy has enhanced the efficacy of immunotherapy upon abrogation of ADAM12 using in vivo murine breast cancer model." (PMID 38715072, 2024). "Hypomethylated promoters with the upregulated gene expressions of PD-1, CTLA4, and TIM3 are reported in primary breast cancer tissues, and CTLA4 and TIGIT promoters in colorectal cancer tissues." (PMID 37460953, 2023). "Another preclinical study investigated the ability of the CA4P analogue (Oxi4503) to improve the responsiveness to immune checkpoint inhibitors (ICIs, namely, PD-1, PD-L1, CTLA-4) of resistant murine mammary carcinoma (C3H)." (PMID 37655095, 2023). "In conclusion, future directions for CTLA-4-based breast cancer immunotherapy include combination therapy and individualized treatment, and the complex mechanisms governing CTLA-4 immunotherapy will continue to be explored." (PMID 37860188, 2023). "We systematically summarize the latest research and clinical advances in CTLA-4-based immunotherapy for breast cancer, providing new perspectives on the treatment of breast cancer." (PMID 37860188, 2023). "CTLA4 and PD-L1, both known as two immunosuppressants commonly used in breast cancer, showed higher expression levels in DJ-1 high expression group (P=0.03 for CTLA4 and P = 1.11 × 10−9 for PD-L1)." (PMID 38125697, 2023). "In the emerging era of immunotherapy, CTLA-4 expression in breast cancer is a potential clinical marker and a rational therapeutic target." (PMID 38406785, 2023). "The level of CTLA-4 in the serum of breast cancer patients is significantly higher than that in the serum of healthy individuals." (PMID 37860188, 2023). "This article focuses on the mechanism of CTLA-4 and the recent research progress of CTLA-4 inhibitors in monotherapy or combination therapy in breast cancer." (PMID 37860188, 2023). "CTLA-4 monotherapy has been successful in cell and animal models of breast cancer and is being evaluated in numerous clinical trials involving patients with a variety of cancers." (PMID 37860188, 2023). "One or two fractions of 12 Gy delivered to murine breast carcinoma together with an anti-CTLA4 antibody led to improved survival in mice when compared with RT or anti-CTLA4 therapy alone." (PMID 37298262, 2023). "We therefore investigated the correlation between A2AR and CTLA-4 expression in our breast cancer patients." (PMID 37753093, 2023). "Similar results were observed in poorly immunogenic metastatic mouse mammary carcinoma treated with a combination of radiotherapy and CTLA-4 blockade." (PMID 37443821, 2023). "Researchers have explored combining CTLA-4 inhibitors with other ICIs or drugs to enhance immune responses in breast cancer." (PMID 37860188, 2023). "The immunotherapeutic efficacy of CTLA-4 inhibitors in breast cancer has been validated in numerous clinical studies." (PMID 37860188, 2023). "This review focuses on the mechanisms of CTLA-4 inhibitor monotherapy or combination therapy in breast cancer." (PMID 37860188, 2023). "The 4T1 transplanted breast cancer mouse model in GSE130472 was subjected to anti-PD-L1 and anti-cytotoxic T-lymphocyte-associated protein 4 (CTLA4) therapies." (PMID 37340461, 2023). "Researchers are combining CTLA-4 inhibitors with other treatments to improve the outcomes of breast cancer patients." (PMID 37860188, 2023).
breast carcinoma (continued). "McKernan also incorporated annexin A5 (ANXA5)-functionalized single-walled carbon nanotubes (SWCNTs) and photothermal therapy into the treatment of primary breast cancer in mice receiving anti-CTLA-4 antibody therapy." (PMID 37860188, 2023). "validated the combined impact of SS1P or LMB-100 alongside anti-CTLA-4 antibody treatment in the 66C14 BALB/c mouse mammary carcinoma cell line." (PMID 37860188, 2023). "One of these trials focuses on the number of adverse events as the primary outcome of cryoablation, Nivolumab (anti-PD-L1), and Ipilimumab (anti-CTLA-4) treatment in patients with early-stage breast cancer." (PMID 37686548, 2023). "Not limited to breast cancer, CTLA-4-targeting immunotoxins displayed analogous effects in the AE17-M mesothelioma model." (PMID 37860188, 2023). "Another CTLA-4 inhibitor, tremelimumab, has also displayed therapeutic potential for treating breast cancer according to recent clinical evidence." (PMID 36765782, 2023). "They further applied a short-term diphtheria toxin (DT) and combined it with anti-CTLA-4 and anti-PD-1 antibodies in a mouse model of breast cancer." (PMID 37860188, 2023). "There have been some studies reporting an association of its increased levels with advanced disease clinical stage, emphasizing CTLA-4’s importance in the development and progression of breast cancer." (PMID 37046635, 2023). "Apart from the combined use of two ICIs, anti-CTLA-4 antibodies have also been employed in conjunction with other drugs for the treatment of breast cancer." (PMID 37860188, 2023). "The results revealed that the incorporation of anti-CTLA-4 antibody enhanced the anticancer activity of lymphocytes and significantly arrested breast cancer cells in the G1/S stage of the cell cycle." (PMID 37860188, 2023). "For instance, a phase I/II study (NCT05187338) is currently testing the triplex CTLA4/PD1/PDL1 inhibitors combination therapy for advanced solid tumors (including breast cancer)." (PMID 36765782, 2023). "An ongoing phase II study is also evaluating the combination therapy of nivolumab (PD-1 inhibitor) and ipilimumab (CTLA-4) in patients with breast cancer (NCT03789110)." (PMID 36765782, 2023). "For instance, T-DM1 (ado-trastuzumab emtansine) has been found to enhance the curative effect of CTLA-4/PD-1 blockades for breast cancer." (PMID 36765782, 2023). "A pilot study of preoperative ipilimumab (anti-CTLA-4) and cryoablation in 19 women with early-stage breast cancer was conducted to determine the safety and tolerability of monotherapy and combinational therapy." (PMID 37860001, 2023). "The anti-CTLA-4 ipilimumab, approved to treat metastatic melanoma, is under consideration for use in combined treatments for breast cancer, to prevent T cell anergy." (PMID 37662839, 2023). "According to several clinical trials of CTLA-4 inhibitors, breast cancer patients experience a variety of irAEs during treatment." (PMID 37860188, 2023). "For instance, increased expression of ICOS was observed on CD4+ T cells from peripheral blood and tumor tissues of patients receiving anti-CTLA4 therapy in several types of cancer, including breast cancer, lung cancer, and bladder cancer." (PMID 38127899, 2023). "CTLA-4, a pivotal immune regulatory molecule, has already shown potential in breast cancer immunotherapy." (PMID 37860188, 2023). "The results showed that DCs produced more cytokines and had greater antigen-presentation capacity, which induced the apoptosis of CTLA-4+ breast cancer cells." (PMID 37860188, 2023). "applied a combination of anti-CTLA-4 antibody, BEmpeg, and radiation therapy to a 4T1 breast cancer mouse model." (PMID 37860188, 2023). "Some studies have analyzed the CTLA-4 expression among different types of breast cancer in The Cancer Genome Atlas (TCGA), it is demonstrated that the expression of CTLA-4 is found to be the highest in TNBC." (PMID 37660039, 2023).
breast carcinoma (continued). "It was observed in a recent study that the high CTLA-4 expression found in the cells of breast cancer is a prediction of the worst prognosis through antitumor immunity suppression." (PMID 38186404, 2023). "Patients with breast cancer were further evaluated for their responses to anti-CTLA-4 immunotherapy and anti-PD-1 immunotherapy, taking into account the variations in the ICI landscape based on risk stratification." (PMID 37543427, 2023). "In another pre-clinical study, anti-CTLA-4 was administered in mammary tumor mouse models either 7 days before, 1 day after, or 5 days after RT and the best tumor control was achieved when anti-CTLA-4 was given prior to RT." (PMID 38069095, 2023). "tested the effects of [Fam-] trastuzumab deruxtecan in combination with anti-CTLA-4 antibody in a mammary tumor mouse model." (PMID 37860188, 2023). "The best-defined mechanisms of immune evasion in breast cancer include the production of suppressive immunostimulatory molecules (PD-L1, CTLA4, and LAG-3), abnormal maturation of DCs, and invasion of immunosuppressive cell populations (MDSCs, Tregs, and TAMs)." (PMID 36900322, 2023). "For example, monoclonal antibodies or bispecific antibodies corresponding to antigens such as EGFR, VEGFR, PD-L1, TGFB1, and CTLA-4 have been used to treat tumors, such as acute lymphoma leukemia, colorectal cancer, and breast cancer." (PMID 36523779, 2022). "Co-administration of T-DM1 with anti-CTLA-4/PD-1 also attenuated tumor cell resistance to ICIs in a HER2-expressing orthotopic breast cancer model." (PMID 34980128, 2022). "In fact, in murine breast cancer models, the effects of radiotherapy and anti-CTLA-4 immunotherapy are dependent upon the presence of invariant natural killer T cells." (PMID 36387071, 2022). "Currently, antibody-mediated blockade of the PD-1/CTLA-4 pathways is an effective way to establish sustained immune responses and treat multiple cancers, including breast cancer, in clinical practice and ongoing trials." (PMID 35154121, 2022). "CTLA-4 was expressed and functional on human breast cancer cells through influencing maturation and function of DCs in vitro." (PMID 35563727, 2022). "A significant correlation has been reported between CTLA-4 and FoxP3 expression in PBMCs of patients with breast cancer." (PMID 36146549, 2022). "Next, we determined the impact of salt diet modification on the anti-tumor efficiency of anti-CTLA4 mAb based ICI therapy in our murine breast cancer model." (PMID 35741331, 2022). "NCT02833233 is a trial in progress in which the safety of combining Nivolumab (anti-PD-l), Ipilimumab (anti-CTLA-4) and cryoablation is being examined for women with early stage breast cancer." (PMID 36389815, 2022). "It has been reported that SLC-0111 by reducing extracellular acidification, augmented the effects of immune-checkpoint inhibitors anti–PD-1 and anti–CTLA-4 on enhancement of Th1 response and reduction of melanoma tumor growth and breast cancer metastasis." (PMID 35365193, 2022). "The application of PD-1/PD-L1 and CTLA-4 have been shown good curative effect on improving patients’ prognosis in hepatocellular carcinoma, non-small cell lung carcinoma, breast cancer and so on." (PMID 36406134, 2022). "Specifically, combined local radiation with anti-CTLA-4 immune checkpoint inhibition in a poorly immunogenic murine breast cancer model resulted in prolonged survival and decreased lung metastases." (PMID 36387071, 2022). "Anti-CTLA-4 and anti-PD-1 loaded scaffolds were implanted directly at the surgical site after the removal of orthotopic 4T1 breast cancer tumors." (PMID 35890247, 2022). "The expression of inhibitory receptors can also significantly impact cDC1 function and high expression of PD-L1, TIM-3 and cytotoxic T lymphocyte antigen 4 (CTLA-4) have been observed on cDC1s within human breast cancers." (PMID 36230990, 2022).
breast carcinoma (continued). "Among the subgroup of basal-like breast cancers, there was a significant effect of a higher expression of CPS (calculated from LAG-3, CTLA-4 and PD-1) being associated with a longer MFS (p = 0.05, log-rank)." (PMID 36289918, 2022). "On the other hand, an LS diet significantly reduced the irAE response following anti-CTLA4 mAb therapy in our breast-cancer-based preclinical murine model." (PMID 35741331, 2022). "Only two of these mentioned studies, including one on rectal cancer patients and the other on breast cancer, had significant results, however, opposing alterations in CTLA-4 expression." (PMID 35967381, 2022). "4T1 breast cancer-bearing mice were treated systemically with AS1411-SMG1 AsiC in combination with anti-CTLA-4/PD-1 antibodies." (PMID 35991316, 2022). "Immunotherapy is the novel treatment for breast cancer, where PD-1 and CTLA-4 antibodies have shown evidence of immune modulation in breast cancer drug trials." (PMID 35799609, 2022). "It has been shown that CTLA-4 can also be expressed on breast cancer cells and induces a suppressive effect on DCs by downregulation of costimulatory markers and HLA-DR." (PMID 36230990, 2022). "It has also been examined the levels and prognostic values of 50 ICR genes in molecular subgroups of breast cancer, including PD-1, CTLA-4, TIGIT, LAG-3, and TIM-3." (PMID 36271406, 2022). "However, breast cancer is a complex disease, with each molecular subtype exhibiting a heterogeneity of response to checkpoint blockade therapy, as well as varying PD-L1 and CTLA-4 expression, nonsynonymous tumor mutational burden, and expression of pro-inflammatory cytokines." (PMID 36295867, 2022). "In the past few decades, most of the studies have been focused on the role of PD1/PDL1 and CTLA-4 in breast cancer, while few studies paid attention to the potential role of CD80." (PMID 35814211, 2022). "In the 4T1-induced breast cancer model, the combination therapy with GSK484 and dual checkpoint blockade of PD-1 and cytotoxic T-lymphocyte-associated protein 4 (CTLA-4) showed synergistic enhancement of the effects of both monotherapies." (PMID 36555469, 2022). "The main immune checkpoints for breast cancer include CTLA-4, PD-1/PD-L1, lymphocyte activation gene 3 (LAG-3), T-cell immunoglobulin domain and mucin 3 (TIM-3), and other molecules." (PMID 35603151, 2022). "Immune checkpoint inhibitors (ICIs) targeting CTLA-4, PD-1, and PD-L1 have been used in the treatment of other solid tumors, but have shown little success in breast cancer." (PMID 36092879, 2022). "The CTLA-4 antagonists’ tremelimumab and ipilimumab have been used in small breast cancer trials, with evidence of downregulating Tregs tumor infiltration in breast cancer." (PMID 36147736, 2022). "In this study we tried to evaluate the Immunohistochemical expression of VDR and CTLA4 antidodies and their role in breast cancer of Egyptian patients as there is a great controversy about their role in suppression or promotion of breast cancer." (PMID 33906311, 2021). "Immune checkpoint inhibitors (ICI) targeting programmed cell death-1 (PD-1) or cytotoxic T lymphocyte antigen-4 (CTLA-4) pathways have made great progress in breast cancer treatment." (PMID 34631507, 2021). "Altogether, our study revealed that anti-CTLA-4 and anti-PD-1 treatment can improve lymphocytes effects on breast cancer cells." (PMID 34440813, 2021). "We observe a similar abscopal response following targeted photothermal ablation and anti-CTLA-4 blockade in the EMT6 model of breast cancer." (PMID 33411055, 2021). "Pre-clinical data demonstrated that anti-CD73 monoclonal antibodies (mAbs) significantly enhanced the activity of anti-CTLA-4 and anti-PD-1 mAbs in animal studies of colon, prostate, and breast cancer." (PMID 34868953, 2021).